UBE3A (ubiquitin protein ligase E3A)
Description:
E3 ubiquitin-protein ligase which accepts ubiquitin from an E2 ubiquitin-conjugating enzyme in the form of a thioester and transfers it to its substrates. Several substrates have been identified including the BMAL1, ARC, LAMTOR1, RAD23A and RAD23B, MCM7 (which is involved in DNA replication), annexin A1, the PML tumor suppressor, and the cell cycle regulator CDKN1B. Additionally, may function as a cellular quality control ubiquitin ligase by helping the degradation of the cytoplasmic misfolded proteins. Finally, UBE3A also promotes its own degradation in vivo. Plays an important role in the regulation of the circadian clock: involved in the ubiquitination of the core clock component BMAL1, leading to its proteasomal degradation. Acts as transcriptional coactivator of progesterone receptor PGR upon progesterone hormone activation. Acts as a regulator of synaptic development by mediating ubiquitination and degradation of ARC (By similarity). Required for synaptic remodeling in neurons by mediating ubiquitination and degradation of LAMTOR1, thereby limiting mTORC1 signaling and activity-dependent synaptic remodeling (By similarity). Synergizes with WBP2 in enhancing PGR activity.
Synonyms: EPVE6AP; HPVE6A; AS; ANCR; E6-AP; FLJ26981; PIX1
Tractability: Small molecule: it has a binding pocket of medium quality. PROTAC: ubiquitination databases record sites on it; its protein half-life has been measured.
Target class: Enzyme; Transferase
Gene: Protein-coding gene on chromosome 15 (25,333,728 to 25,439,092, reverse strand). Ensembl gene ENSG00000114062.
Subcellular location: Cytoplasm; Nucleus
Subcellular location (Human Protein Atlas): Nucleoplasm; Cytosol
Pathways (Reactome):
Immune System: Antigen processing: Ubiquitination & Proteasome degradation
Gene Ontology:
Molecular function: protein binding; ubiquitin protein ligase activity; ubiquitin-protein transferase activity; transcription coactivator activity
Biological process: positive regulation of protein ubiquitination; progesterone receptor signaling pathway; protein autoubiquitination; protein K48-linked ubiquitination; regulation of circadian rhythm; regulation of ubiquitin-dependent protein catabolic process; response to progesterone; brain development; negative regulation of TORC1 signaling; proteasome-mediated ubiquitin-dependent protein catabolic process; protein polyubiquitination; proteolysis; regulation of synaptic plasticity; ubiquitin-dependent protein catabolic process; animal organ development; Golgi lumen acidification; modulation of chemical synaptic transmission; nuclear receptor-mediated steroid hormone signaling pathway; positive regulation of DNA-templated transcription; protein ubiquitination; system development
Cellular component: cytoplasm; cytosol; nucleus; glutamatergic synapse; postsynaptic cytosol; synaptic vesicle
Genetic constraint (gnomAD): Loss-of-function variants: 6 observed, 85.11 expected, observed/expected ratio (o/e) 0.0705, 90% interval 0.038 to 0.14. The upper end of that interval is the gene's LOEUF score, 0.14, which puts it in group 1 of 6, group 1 being the genes least tolerant of losing a copy. Missense variants: 456 observed, 1,082.6 expected, observed/expected ratio (o/e) 0.42, 90% interval 0.39 to 0.46. Synonymous variants: 337 observed, 366.84 expected, observed/expected ratio (o/e) 0.92, 90% interval 0.84 to 1.
Gene-disease validity (ClinGen):
ClinGen rates the evidence that UBE3A causes each of these diseases.
Angelman syndrome (autosomal dominant): Definitive. A neurogenetic disorder characterized by severe intellectual deficit and distinct facial dysmorphic features.
Homologues: Orthologues: chimpanzee UBE3A (99% identical), rabbit UBE3A (99% identical), dog UBE3A (98% identical), guinea pig UBE3A (98% identical), pig UBE3A (98% identical), macaque UBE3A (97% identical), rat Ube3a (96% identical), mouse Ube3a (96% identical), tropical clawed frog ube3a (92% identical), zebrafish ube3a (85% identical), Drosophila melanogaster Ube3a (45% identical). Paralogues in human: HERC4 (26% identical), HERC3 (25% identical), HERC6 (24% identical), HERC5 (23% identical), HERC2 (21% identical), HECTD2 (21% identical), HECW2 (19% identical), HECW1 (18% identical), HUWE1 (18% identical), HECTD1 (17% identical), SMURF2 (17% identical), WWP1 (17% identical), and 12 more.
Diseases named in the same sentence as UBE3A in open-access papers:
UBE3A is named in the same sentence as 168 diseases in open-access papers, as found by Europe PMC text mining. Sharing a sentence is not in itself a finding about the gene and the disease. The quoted sentences say what the papers report.
Angelman syndrome (357 papers, 2005 to 2026). "Angelman syndrome (AS) is a neurodevelopmental disorder caused by the loss of maternal UBE3A expression, leading to disrupted proteostasis and synaptic dysfunction." (PMID 42201242, 2026). "Angelman syndrome is a neurodevelopmental disorder caused by loss of the maternal UBE3A allele, the sole source of UBE3A in mature neurons owing to epigenetic silencing of the paternal allele." (PMID 41632831, 2026). "Angelman syndrome (AS) is a neurodevelopmental disorder caused by the loss of the maternal allele of the UBE3A gene, which encodes a protein essential for ubiquitin-mediated protein degradation." (PMID 42164230, 2026). "Angelman Syndrome (AS) is a neurodevelopmental disorder caused by the deficiency of the UBE3A gene that for a E3 ligase protein part of the ubiquitin–proteasome system (UPS)." (PMID 41303513, 2025). "Angelman syndrome (AS) is a single-gene neurodevelopmental disorder caused by loss of function of the maternal copy of the UBE3A gene." (PMID 39989972, 2025). "Mutations or imprinting errors that disrupt expression of the maternal allele results in reduction or complete loss of UBE3A gene expression, causing Angelman syndrome (AS), a disorder characterized by ASD features." (PMID 41149794, 2025). "Under normal conditions, UBE3A mediates the ubiquitination of substrates involved in cell signaling and neuronal development, and UBE3A loss of function in brain causes Angelman syndrome, a neurodevelopmental disorder." (PMID 40002221, 2025). "The functional importance of this invariant glycine is reinforced by the UBE3A/E6AP G738E mutation, which causes Angelman syndrome." (PMID 40179885, 2025). "Angelman syndrome (AS) is a rare neurodevelopmental disorder caused by loss of expression of the maternal UBE3A allele and is characterized by a constellation of impactful neurologic symptoms." (PMID 40935670, 2025). "In Angelman syndrome (UBE3A mutations), >80% of patients show intermittent rhythmic delta activity with frontal notching and ~75% show epileptiform discharges." (PMID 40968989, 2025). "Studies have previously shown that UBE3A loss of function leads to Angelman syndrome, a complex severe neurological genetic disorder, suggesting that UBE3A has a critical role in the normal development and function of the CNS." (PMID 40470739, 2025). "Loss or loss of function of the maternal allele leads to a dearth of UBE3A and is the primary linkage to the neurodevelopmental disorder, Angelman Syndrome (AS)." (PMID 40950402, 2025). "In Angelman syndrome, the maternal copy of the gene-encoding ubiquitin ligase E3A (UBE3A) is lost, and the paternal copy of the gene is imprinted and thus not expressed in brain neurons." (PMID 40650152, 2025). "Angelman Syndrome is a debilitating neurological disorder caused by neuronal loss of function from the E3 ubiquitin ligase UBE3A." (PMID 40877933, 2025). "Angelman syndrome (AS), a severe neurodevelopmental disorder caused by loss of neuronal UBE3A, is characterized by symptoms such as motor impairment, lack of speech, seizures, and disrupted sleep." (PMID 40935670, 2025). "UBE3A is widely associated with Angelman syndrome, which is caused by deletion or mutation of maternal UBE3A." (PMID 40316779, 2025). "There are four molecular mechanisms underlying Angelman syndrome: maternal deletion of 15q11-q13, UBE3A mutations, paternal uniparental disomy, and imprinting defects." (PMID 41200642, 2025). "Angelman syndrome is a rare neurodevelopmental disorder caused by the loss of function of the maternally inherited UBE3A gene within the chr15q11-q13 region." (PMID 40956516, 2025). "Angelman Syndrome (AS) is characterized in large part by the loss of functional UBE3A protein in mature neurons." (PMID 40950402, 2025). "In Angelman syndrome, this tissue-specific form of imprinting prevents paternal UBE3A from compensating for maternal loss of this gene causing the disease." (PMID 40956516, 2025).
Angelman syndrome (continued). "UBE3A loss-of-function mutation has been observed in individuals with Angelman syndrome, while autism-linked UBE3A gain-of-function mutation was recently reported in a mouse model showing neurobehavioral deficits." (PMID 41223260, 2025). "UBE3A mutations cause Angelman syndrome, where UBE3A deficiency disrupts synaptic development, neural circuit formation, and brain function during critical developmental stages." (PMID 40943197, 2025). "Angelman syndrome is a rare neurodevelopmental disorder caused by a defect in the UBE3A gene, leading to characteristic neurological and behavioral manifestations." (PMID 41200642, 2025). "The loss of maternal UBE3A causes Angelman syndrome whereas its duplication is associated with a heterogeneous neurodevelopmental disorder." (PMID 40316779, 2025). "The enrichment of genes downstream of IRF has been observed in a UBE3A-deficient mouse model of Angelman syndrome." (PMID 40076922, 2025). "This region partially overlaps with 15q11-q13, which is implicated in Angelman syndrome due to deletions or mutations in the maternal copy of the UBE3A gene." (PMID 41200642, 2025). "Angelman syndrome (AS) results from the epigenetic silencing of the paternal ubiquitin protein ligase E3A (UBE3A) allele in neurons." (PMID 41455872, 2025). "Intracellular localization and biochemical analyses revealed that 55% of the variants found in patients with Angelman syndrome induced the mislocalization of UBE3A, and 29% of the variants induced a loss of E3 ligase activity." (PMID 40299435, 2025). "Angelman syndrome is caused by an abnormality in the maternally expressed UBE3A gene on chromosome 15q11-q13, which encodes an E3 ubiquitin ligase essential for neurological function." (PMID 41200642, 2025). "Angelman syndrome (AS) is a rare (1:20,000) neurogenetic syndrome caused by the loss of the maternal ubiquitin-protein ligase E3A (UBE3A) gene in the 15th chromosome." (PMID 40235515, 2025). "Angelman syndrome is a rare neurodevelopmental genetic disorder caused by abnormalities in the UBE3A gene located on chromosome 15q11-q13." (PMID 41200642, 2025). "In individuals with Angelman Syndrome, the paternal allele of the UBE3A gene is silenced, and the loss of function of the maternal allele leads to the disease." (PMID 40469903, 2025). "Pathogenic variants of the ubiquitin protein ligase E3A (UBE3A) cause the Angelman syndrome (AS), which is a neurodevelopmental disorder that is frequently associated with ASM-resistant DRE." (PMID 40290041, 2025). "Angelman syndrome (AS) is a rare genetic disorder due to lack of UBE3A function on chromosome 15q11.2q13 caused by a deletion, uniparental paternal disomy (UPD), imprinting center disorder (ICD), or pathological variant of the UBE3A gene." (PMID 37831301, 2024). "The demonstration that ube3A mutants exhibit hyperactivation of BMP signaling at the Drosophila NMJ is of particular interest as Ube3A is associated with neurodevelopmental defects in Angelman syndrome and autism." (PMID 38124338, 2024). "UBE3A is subject to DNAm-dependent genomic imprinting and is associated with Angelman syndrome, a neurodevelopmental disorder characterized by severe intellectual disability." (PMID 39513881, 2024). "Angelman syndrome (AS), a severe neurodevelopmental disorder resulting from the loss of the maternal UBE3A gene, is marked by changes in the brain’s white matter (WM)." (PMID 39149488, 2024). "Loss of Ube3a/E6AP, the causative gene for Angelman syndrome, results in abnormal acidification of the Golgi apparatus and protein sialylation." (PMID 39079741, 2024). "Angelman syndrome (AS) is a neurodevelopmental disorder caused by loss of function of the ubiquitin–protein ligase E3A (UBE3A) gene, which, in almost all neurons, is expressed only from the maternal chromosome 15." (PMID 38580983, 2024).
Angelman syndrome (continued). "Angelman syndrome (AS) is a neurogenetic disorder caused by mutations or deletions in the maternally-inherited UBE3A allele, leading to a loss of UBE3A protein expression in neurons." (PMID 38873093, 2024). "The gene product of UBE3A is responsible for protein degradation in a cell and deletion of the gene causes Angelman syndrome." (PMID 39202440, 2024). "The last patient had Angelman syndrome (UBE3A germline variant) and died at the age of 6.5 years due to kidney failure and withholding of kidney replacement therapy." (PMID 39698353, 2024). "Ube3a is an E3 ubiquitin-protein ligase important for the degradation of cytoplasmic misfolded proteins that is mutated in Angelman syndrome, a human neurodevelopmental disorder caused by loss of function of the maternally inherited UBE3A." (PMID 38471806, 2024). "Deletion of the maternal UBE3A allele causes Angelman syndrome (AS); because paternal UBE3A is epigenetically silenced by a long non-coding antisense (UBE3A-ATS) in neurons, this nearly eliminates UBE3A protein in the brain." (PMID 38977672, 2024). "Angelman syndrome (AS) is a neurodevelopmental disorder caused by abnormal expression of the maternal ubiquitin protein ligase E3A gene (UBE3A)." (PMID 38580983, 2024). "The activity-loss of the maternally inherited UBE3A and paternally inherited overexpression of UBE3A (PatUPD15q) cause the Angelman syndrome with a typical autistic phenotype." (PMID 39336109, 2024). "Mutations and deletions in the UBE3A gene account for the five molecular mechanisms which cause Angelman Syndrome." (PMID 39108836, 2024). "Angelman syndrome (AS) is a rare neurodevelopmental genetic disorder caused by the loss of function of the ubiquitin ligase E3A (UBE3A) gene, affecting approximately 1:15,000 live births." (PMID 39049050, 2024). "UBE3A plays a role in synaptic plasticity and loss-of-function mutations in the UBE3A gene are associated with Angelman syndrome and Prader-Willi syndrome." (PMID 36926679, 2023). "Mutations in the gene encoding UBE3A occur on chromosome 15q11 in patients with Angelman syndrome and some ASD patients." (PMID 36768153, 2023). "Angelman syndrome (AS) is a rare neurogenetic disorder caused by UBE3A deficiency and characterized by severe developmental delay, cognitive impairment, and motor dysfunction." (PMID 37903805, 2023). "WES was used to diagnose Patient #14, a two-year-and-ten-month-old child with Angelman syndrome (AS) due to a point mutation in exon 9 of the UBE3A gene." (PMID 37878632, 2023). "Angelman Syndrome is a neurological disorder caused by a mutation of the E3 ubiquitin ligase UBE3A, a gene whose mutation is associated with autism spectrum disorders." (PMID 37483450, 2023). "One of the ubiquitin related genes is UBE3A (ubiquitin protein ligase E3A), a maternally expressed gene on chromosome 15 that causes Angelman syndrome, an imprinted disorder, and when it is mutated, it shows features of autism." (PMID 36980949, 2023). "The gain of function mutations, triplication, or duplication in the UBE3A gene is also associated with ASDs like Angelman Syndrome (AS) and Dup15q Syndrome." (PMID 38248358, 2023). "Angelman syndrome (AS) is a neurodevelopmental disorder caused by the loss of function of the maternally expressed gene UBE3A, located on chromosome 15q11–q131." (PMID 37069177, 2023). "Angelman syndrome occurs due to the loss of function of the maternal ubiquitin-protein ligase E3A (UBE3A) gene located in the 15q11.2–13.3 region and is characterized by the appearance of epilepsy, motor abnormalities, intellectual disability, or autism." (PMID 37190119, 2023). "Angelman syndrome is a neurodevelopmental disorder caused by loss of function of the maternally expressed UBE3A gene." (PMID 37069177, 2023).